DSP (desmoplakin)
Diseases named in the same sentence as DSP in open-access papers (continued):
Sharing a sentence is not in itself a finding about the gene and the disease.
Carvajal syndrome (continued). "Patients with pathogenic mutations in the DSP gene frequently presented with a comparable triad of clinical features consisting of DCM, wooly hair, and palmoplantar keratoderma, which is known as Carvajal syndrome (MIM, #605676)." (PMID 32670084, 2020). "Desmoplakin has also roles in Carvajal syndrome, relating to hair abnormalities and altered skin." (PMID 32411128, 2020). "In dermatology, DSP mutations are mainly associated with two syndromes: Carvajal syndrome, which involves mutations in the C-terminal tail of DSP and affects both the skin and heart, and SFWHS, first described in 2011, caused by mutations in the N-terminal head of DSP." (PMID 41502835, 2026). "In contrast, although DSP is also associated with multiple phenotypes (including DCM, DCM with cutaneous features, ARVC, and Carvajal syndrome), these are overlapping and it does not appear that distinct mechanisms drive different presentations." (PMID 37872640, 2023).
Palmoplantar keratoderma (23 papers, 2007 to 2026). Abnormal thickening of the skin of the palms of the hands and the soles of the feet. "This gene encodes a desmosomal protein that is critical to cell-cell adhesion; mutations in DSP have been proven to cause palmoplantar keratoderma, skin fragility, or woolly hair syndrome." (PMID 39092175, 2024). "The cutaneous phenotype related to DSP variants includes curly or wavy hair and palmoplantar keratoderma (PPK), the epidermal thickening of the palms and soles." (PMID 37008330, 2023). "Recessive mutations in DSP (the desmoplakin gene) have been associated with palmoplantar keratoderma, acantholytic epidermolysis bullosa, dermatitis, and extensive skin erosion." (PMID 37188635, 2023). "The skin fragility-woolly hair syndrome (OMIM 607,655) represents another recessive disorder due to desmoplakin mutations characterized by palmoplantar keratoderma, woolly hair, variable alopecia, dystrophic nails, and excessive blistering." (PMID 34996433, 2022). "DSP gene mutation can produce phenotypes of curly hair such as skin fragility–woolly hair syndrome involving the desmosomes; syndromes caused by mutation in the DSP gene include palmoplantar keratoderma, woolly hair, and variable alopecia." (PMID 36423088, 2022). "Mutations in DSP have been linked to several Mendelian syndromes involving palmoplantar keratoderma, left ventricular cardiomyopathy, familial arrhythmogenic right ventricular dysplasia, and lethal ancantholytic epidermolysis bullosa." (PMID 31324189, 2019). "Autosomal recessive cases due to desmoplakin mutations also have features that overlap with PC, including palmoplantar blistering and keratoderma with nail dystrophy, which can lead to misdiagnosis." (PMID 24611874, 2014). "Additionally, extra-cardiac features have been described in patients with pathogenic DSP variants, namely woolly hair and palmoplantar keratoderma." (PMID 36434384, 2023). "Interestingly, in a case report of a 14-year-old child with extensive mucocutaneous blisters caused by acantholysis of keratinocytes, epidermolytic palmoplantar keratoderma, nail dystrophy, enamel dysplasia, and sparse woolly hair, a very similar DSP missense variant was found." (PMID 34996433, 2022). "A typical cutaneous phenotype, with wooly hair and/or palmoplantar keratoderma, was reported in a significant percentage of DSP carriers, ranging from 44% to 55%." (PMID 37048743, 2023). "Cardiocutaneous syndrome (CCS) is often caused by genetic variants in desmoplakin (DSP) in the presence of thick calluses on the hands and soles of the feet (palmoplantar keratoderma) in combination with arrhythmogenic cardiomyopathy." (PMID 36769561, 2023).
heart failure (19 papers, 2014 to 2026). Inability of the heart to pump blood at an adequate rate to meet tissue metabolic requirements. "Especially arrhythmogenic left ventricular cardiomyopathy (ALVC) patients are likely to combine with PLN and DSP variants and are associated with a high risk of heart failure." (PMID 39845823, 2024). "Here, we present a patient with LV‐predominant ACM caused by a novel p.Q1830 mutation in the desmoplakin (DSP) gene, resulting in progressive heart failure and a spectrum of electrophysiological abnormalities." (PMID 38827944, 2024). "PKP2 carriers were least likely to have LV dysfunction (9%), whereas those with a P/LP DSP variant had significantly more frequent LV dysfunction (40%) and heart failure (13%)." (PMID 34926342, 2021). "In mutation positive ARVD/C, DSP carriers are associated with four-fold higher likelihood of sudden cardiac death, LV dysfunction, and heart failure compared to PKP2 carriers." (PMID 34011348, 2021). "Patients with DCM who carry pathogenic variants in the LMNA, RBM20, and DSP genes are at higher risk for heart failure progression and may require heart transplantation." (PMID 38999368, 2024). "In addition, the presence of certain DSP variants may be useful in recognizing higher-risk phenotypes in patients who will develop arrhythmias and heart failure at follow-up." (PMID 39336825, 2024). "Arrhythmogenic cardiomyopathy (ACM) is a genetic form of heart failure that affects 1 in 5,000 people globally and is caused by mutations in cardiac desmosomal genes including PKP2, DSP, and DSG2." (PMID 42090754, 2026). "Arrhythmogenic cardiomyopathy (ACM) is a genetic form of heart failure that affects 1 in 5000 people globally and is caused by mutations in cardiac desmosomal proteins including PKP2, DSP, and DSG2." (PMID 39763850, 2024). "PKP2 variants are associated with more arrhythmias and classical RV-dominant ACM while desmoplakin (DSP) and desmoglein-2 (DSG2) pathogenic variants are associated with more heart failure." (PMID 38137480, 2023). "Cell death and myocardial fibrosis are the cardinal features of heart failure and hereditary cardiomyopathies, particularly ACM caused by mutations in the human DSP gene." (PMID 36818425, 2023). "In addition, individuals with a mutation in the phospholamban or desmoplakin gene (especially when involving the C-terminus of desmoplakin) have significant left-dominant/biventricular disease expression and a high prevalence of heart failure." (PMID 25191878, 2014). "Variants in DSP are estimated to occur in 3% of European individuals with DCM; although they have been historically implicated in ARVC, we demonstrate that disease-causing non-missense DSP variants manifest with a high burden of LV injury, LV dysfunction, heart failure, and arrhythmic events." (PMID 35083019, 2022).
Arrhythmia (17 papers, 2020 to 2025). Any cardiac rhythm other than the normal sinus rhythm. "The VCL and TTN variants were inherited from the mother who had a normal echocardiogram but had arrhythmias on Holter monitoring at last follow-up, and the DSP variant was inherited from an unaffected father." (PMID 37548861, 2023). "They formed a ternary assembled with desmin and desmoplakin and showed that deficient iASPP in mice led to ventricular tachycardia, arrhythmia, ACM, and sudden death." (PMID 35933355, 2022). "Studies evaluating the clinical findings in patients with DSP gene mutations reported that pathogenic DSP gene mutations are much more associated with left ventricular cardiomyopathy and a heightened arrhythmia risk, distinct from PKP2, which targets the right ventricle, causing classical ARVC." (PMID 38768074, 2024). "Mutations in the LMNA and DSP genes, particularly associated with inflammation in ACM, require consideration of arrhythmia prevention strategies, such as ICD implantation." (PMID 41040932, 2025). "Disruption of desmoplakin leads to fibrofatty infiltration of the myocardium which leads to congestive heart failure, cardiac arrhythmias, and sudden cardiac death." (PMID 38510230, 2024). "For individuals with DCM and a pathogenic/likely pathogenic variant in a gene correlated with life-threatening arrhythmias (LMNA, FLNC, RBM20, DSP), exercise should be restricted to recreational activities." (PMID 33040239, 2020). "A large-scale clinical study has demonstrated that patients with HCM carrying pathogenic DSP variants exhibit a distinct arrhythmia phenotype, characterized by non-sustained ventricular tachycardia (NSVT), left bundle branch block (LBBB), and biventricular structural remodeling." (PMID 41561115, 2025). "LMNA and SCN5A have long known to be associated with life-threatening ventricular arrhythmias, and the studies of RBM20, DSP, and FLNC discussed here clearly demonstrate significant arrhythmia and sudden death risks." (PMID 33040239, 2020).
lung carcinoma (17 papers, 2013 to 2025). "Of these, rs2076295, associated with lung cancer, is an intronic variant of DSP; the risk allele rs2076295-G has been associated with decreased DSP gene expression in lung." (PMID 37340002, 2023). "We identify ten cancer risk variants including five pleiotropic associations (e.g., rs2076295 at DSP on 6p24 associated with lung cancer and rs2525548 at TRIM4 on 7q22 nominally associated with six cancers)." (PMID 37340002, 2023). "Similarly, DSP was shown to enhance the expression of plakoglobin (also known as γ-catenin) in human lung cancer, which is associated with the suppression of β-catenin." (PMID 32156068, 2020). "For example, elevated expression of desmoplakin and plakoblobin—the two most abundant proteins in desmosomal junction—facilitate breast and lung cancer cells to form clusters and increase their survival in circulation." (PMID 40881990, 2025). "DSP has a tumor suppressive function through inhibition of Wnt/-catenin signalling pathway in human lung cancer." (PMID 38952985, 2024). "DSP has been reported to act as a tumor suppressor by inhibiting the Wnt/β-catenin signaling pathway in human lung cancer." (PMID 31484163, 2019). "Among these 8 desmosomal genes, the most obvious change in expression is three tumor suppressor genes for lung cancer, DSP, JUP and DSC3." (PMID 29855376, 2018). "Yang and his team demonstrated the role of the epigenetic regulation of desmoplakin in increasing the sensitivity of cancer cells to anticancer drug-induced apoptosis, implying the clinical value of desmoplakin for the treatment of patients with lung cancer." (PMID 30081883, 2018). "In human lung cancer, DSP was observed to enhance PG expression and act as a tumor suppressor." (PMID 35078507, 2022). "A previous study reported that DSP could function as a tumor suppressor through inhibition of the Wnt/β-catenin pathway in human lung cancer." (PMID 31484163, 2019). "Contrary to the observation that antagonizing desmoplakin function promotes keratinocyte proliferation, the overexpression of desmoplakin was described to inhibit lung cancer cell proliferation and was accompanied by the downregulation of the Wnt signaling mediator Axin2." (PMID 29373494, 2018). "To further determine the correction between SOX30 and these genes, we tested for expression of SOX30, DSP, JUP and DSC3 in human lung cancer tissues and adjacent tissues." (PMID 29855376, 2018). "The expression of SOX30, DSP, JUP and DSC3 were detected in lung cancer cell lines, lung tissues of mice and patients’ tissues by qPCR, WB, Immunofluorescence and Immunohistochemistry." (PMID 29855376, 2018). "In each meta-analysis of breast and lung cancer across BBJ1 and UKB, we identified one locus newly satisfying the genome-wide significance threshold (breast: rs2800691 at PADI6 on 1p36, P = 3.6 × 10−8; lung: rs2076295 at DSP on 6p24, P = 2.6 × 10−8)." (PMID 37340002, 2023). "The expression analysis of desmoplakin in several cancers showed decreased levels or the absence of this plakin in oral squamous cell carcinomas and carcinomas of the lung." (PMID 29373494, 2018). "According to our observation presented above and considering the facts that DSP and JUP can suppress lung cancer progression by inhibition of the Wnt/β-catenin signaling pathway, we hypothesized that SOX30 can suppress the Wnt/β-catenin signaling pathway through upregulation of DSP and JUP." (PMID 29855376, 2018). "The expression of DSP and JUP are reduced or absent in lung cancer and re-expression results in reduction of cell growth and migration by suppressing the Wnt signaling pathway in lung cancer." (PMID 29855376, 2018).
cardiocutaneous syndrome (16 papers, 2007 to 2026). "Recent advances in genomic technologies have enabled early recognition of DSP mutations, including those leading to cutaneous-limited and cardio-cutaneous syndromes." (PMID 41502835, 2026). "Reported DSP mutations exhibit variable phenotypes, ranging from purely cutaneous involvement to cardiocutaneous syndromes." (PMID 41502835, 2026). "In 2000, the first desmosomal gene variant underlying a cardiocutaneous syndrome was identified as a homozygous DSP variant that translated to a C-terminal truncated desmoplakin protein." (PMID 36142674, 2022). "Over the years, many hundreds of pathogenic variants in DSP have been associated with different cutaneous and cardiac phenotypes or a combination, known as a cardiocutaneous syndrome." (PMID 35325485, 2022). "The reported variants associated with cardiocutaneous syndrome, in genes DSP, JUP, DSC2, KLHL24, GJA1, are classified by interpretation guidelines from the American College of Medical Genetics and Genomics." (PMID 36142674, 2022). "Carvajal disease was later described as another recessive cardiocutaneous syndrome, in this case by mutations in desmoplakin (DSP)." (PMID 34640625, 2021). "Other desmosomal gene variants in JUP, desmoplakin (DSP), and desmocollin 2 (DSC2) have been found in isolated cases of similar cardio-cutaneous syndromes in various parts of the world, from the Mediterranean to Argentina and Ecuador." (PMID 39877668, 2025). "None of the participants with DSP variants presented with woolly hair as a diagnostic clue of a cardiocutaneous syndrome." (PMID 39630431, 2025).
breast carcinoma (15 papers, 2006 to 2025). "Decreased desmoplakin expression is also associated with breast cancer metastasis and invasion." (PMID 39052015, 2024). "It is interesting to note that both desmoplakin, an important constituent of desmosomes, and nicotinate phosphoribosyltransferase, involved in NAD+ biosynthesis, have been linked to breast cancer." (PMID 38928454, 2024). "The subcellular localization of the DSP constructs was assessed by fluorescence microscopy in SUM159 human breast cancer cells." (PMID 31324885, 2019). "WalBC cells showed regulated expression of DSP, s100A14 and ANXA1 which are genes associated with well-differentiated, epithelioid breast cancer cell lines with weak invasive potential and poorly invasive tumors." (PMID 18179684, 2008). "The decreased expression of epiplakin associated with malignancy potential, as observed in our study, may be correlated with the activation of epithelial–mesenchymal transition, similar to the findings reported for desmoplakin in gastric, lung, and breast cancers." (PMID 39052015, 2024). "WalBC cells exhibited expression of known markers of basal invasive human breast cancers as well as increased KRT17, KRT 14 and KRT 19, DSP, s100A4, NDRG-1, ANXA1, TK1 and AQP3 gene expression and decreased gene expression of TIMP3, VIM and TAGLN." (PMID 18179684, 2008).
Ventricular arrhythmia (15 papers, 2020 to 2025). "Pathogenic variantsin DSP gene that modify the basic function of desmoplakin protein areassociated with sustained ventricular arrhythmias and cardiac fibrosis inpatients with DCM." (PMID 39077708, 2022). "Gene variants in DSP have been associated with ventricular arrhythmias." (PMID 39940965, 2025). "Interestingly, in this cohort, carriers of DSP variants showed a higher rate of ventricular arrhythmias (VA), which exceeded the degree of systolic disfunction." (PMID 37048743, 2023). "Patients with DCM linked to DSP variants exhibit a significantly increased risk of SCD and life-threatening ventricular arrhythmias, even when LVEF is only mildly reduced." (PMID 41561115, 2025). "One of the earliest reports of DSP carriers showed a ventricular arrhythmia rate of 46%." (PMID 37048743, 2023). "Patients are predisposed to a wide spectrum of clinical presentations, such as ventricular arrhythmia and SCD, which are associated with mutations in desmosome genes, such as plakoglobin (JUP), desmoplakin (DSP), plakophilin 2 (PKP2), desmoglein 2 (DSG2), and desmocollin 2 (DSC2)." (PMID 35433691, 2022).
Naxos disease (14 papers, 2006 to 2025). A recessively inherited condition with arrhythmogenic right ventricular dysplasia/cardiomyopathy (ARVD/C) and a cutaneous phenotype, characterized by peculiar wooly hair and palmoplantar keratoderma. "In the variant form of Naxos disease, two different mutations in the Desmoplakin gene, affecting the C-terminal of the protein (Dsp7901del1G and DspG2375R), were identified as causative in families from Ecuador and Israel (Arab families)." (PMID 40108711, 2025). "Theidentification of these syndromes led to the discovery of the responsible mutatedgenes: plakoglobin (JUP) for Naxos disease and desmoplakin (DSP) for Carvajaldisease." (PMID 39076647, 2022). "Mutations in the genes encoding the desmosomal proteins plakoglobin and desmoplakin have been identified as the cause of Naxos disease." (PMID 16722579, 2006). "In the Naxos disease variety described in families from Ecuador and Israel (Arab families), two different mutations of the desmoplakin gene (Dsp7901del1G and DspG2375R), affecting the C-terminal of the protein, have been found as causative genes." (PMID 16722579, 2006). "Most of the previously identified gene mutations that underlie ARVC (ARVC 8, 9, 10 and 12 and Naxos disease) are mutations of genes encoding desmosomal proteins: Plakophilin2 (PKP2), Desmoplakin (DSP), Desmoglein2 (DSG2), Desmocollin2 (DSC2) and Junction Plakoglobin (JUP)." (PMID 25343256, 2014). "Naxos disease is caused by a homozygous pathogenic variant in the plakoglobin gene (JUP), leading to ACM (100% penetrance), woolly hair, and palmoplantar keratoderma, whereas in Carvajal syndrome, a recessive homozygous pathogenic variant in the desmoplakin gene (DSP) gives rise to similar symptoms." (PMID 35008484, 2021).